APC (APC regulator of Wnt signaling pathway)
Diseases named in the same sentence as APC in open-access papers (continued):
Sharing a sentence is not in itself a finding about the gene and the disease.
tumor (continued). "Therefore, combining Wnt pathway inhibitors with immunotherapy could enhance anti-tumor immune responses and improve outcomes for patients with APC-mutant CRC." (PMID 39684219, 2024). "Notably, a total of 10 previously reported single-nucleotide polymorphisms (SNPs) were found in this tumor in genes including MLH1 (rs769364808), FGFR3 (rs769364808), two variants (rs1873778 and rs2228230) in PDGFRA, KIT (rs55986963), APC (rs41115), and RET (rs1800861)." (PMID 37273678, 2023). "Notably, enrichment of genes associated with stem cell homeostasis, i.e., Myc and βcat signaling, which is often documented in mutant APC models, was also observed in oncogenic truncated APC-expressing cells and tumor tissue further highlighting the physiological relevance of our data." (PMID 37468468, 2023). "Since APC affected both Wnt/β-catenin signaling and Oct4 expression, we next determined whether Oct4 functioned as a downstream effector to mediate the influence of APC–Wnt/β-catenin signaling on tumor cell self-renewal." (PMID 37746658, 2023). "Increasing evidence suggests that numerous m6A targets contribute to tumorigenesis, including Snail, CTNNB1, NANOG, APC, and genes associated with the Akt/mTOR pathway However, conflicting reports have indicated that METTL3 may function as a tumor suppressor in certain tumor types." (PMID 38012755, 2023). "However, a study found that genetic deficiency of MMP9 enhanced CAC development and reduced survival in AOM/DSS-treated mice suggesting an anti-tumoral role in CAC in contrast to APC-mutation-driven CRC, where genetic deficiency of MMP9 decreased tumour number by 40% in Apcmin/+ mice." (PMID 36263033, 2022). "Thus, the identification of downstream molecular events related to APC has the potential to lead to the identification of genes critical to tumor development, some of which may be modifiable through drug targeting or gene editing." (PMID 35999641, 2022). "However, it still remains unclear which factors induced by strong Wnt/β-catenin signaling in the intestinal tumor cell led to this immense MC migration, as it was seen predominantly in the βCAT and also APC model group." (PMID 35565377, 2022). "The mixture of tumor cells with a risk of malignant transformation (green—fully functional APC activity lost and PI3K activated) and tumor cells with a relatively low risk of malignant transformation (red—fully functional APC activity lost) resulted in a greater invasion of even the green cells." (PMID 34245130, 2022). "When exploring the intracellular pathways on which NLGN1 could impact, we first considered that the tumor suppressor APC is required for localizing NLGN1 to neuronal nicotinic synapses, implicating a functional interaction at the cell membrane of both proteins." (PMID 36056393, 2022). "In agreement with MMRd being the early driving force in the index patient’s tumor, four of the five identified APC variants are frameshift mutations, including the two APC (L)PVs falling in the early mutational burst (VAF of >17.5%), whereas four of five APC (L)PVs of the sister’s tumor are SNVs." (PMID 36291559, 2022). "Therefore, we suspect that the APC gene in human brain tissue plays a decisive role in regulating the occurrence and development of tumors, and drugs that target the APC gene in brain tissue may be useful in tumor intervention." (PMID 35303016, 2022).
tumor (continued). "For example, the last remaining variant from the previously discussed longitudinal example was not recovered in the described analysis (patient #3, APC V1822D) because it was a germline variant that increased in frequency over the time course of the tumor samples." (PMID 33771218, 2021). "If TEs insert into DNA repair genes such as breast cancer type 2 susceptibility protein (BRCA2) or tumor suppressor genes such as adenomatous polyposis coli protein (APC) and retinoblastoma protein 1 (RB1), they may cause genome instability or tumor formation, respectively." (PMID 34364371, 2021). "This is usually explained by the “Just right” model stating that the impairment of APC function in cancer allows sufficient accumulation of β-catenin that facilitates tumor formation, as opposed to complete loss of APC function that leads to excessive β-catenin accumulation triggering apoptosis." (PMID 34552058, 2021). "Truncated APC protein destabilizes the complex and increases the cytoplasmic β-catenin level, which translocates to the nucleus and activates the transcription of various genes involved in tumor growth and invasion, by interacting with the T-cell factor/lymphoid." (PMID 34326875, 2021). "A high-throughput sequencing of the tumor described in both cases alteration in the Wnt/β-catenin pathway: a mutation in CTNNB1 (exon 3, c.110C>G, p.S37C, reported as a hotspot in COSMIC) in one case and a homozygous loss associated with breakage targeting APC (5q22.2) in the second." (PMID 33796447, 2021). "This suggests that decreasing the intracellular metabolism of ATRA, by inhibiting CYP26A1 activity using liarozole, might be a way to increase ATRA levels and augment RA signaling in tumor cells, including the reduction in tumor SC numbers in APC-mutant tissues." (PMID 34299349, 2021). "Furthermore, to confirm the tumor-origin of the PDCOs we have analyzed the expression of PC-associated epigenetic biomarkers including promoter methylation of the GSTP1, RASSF1 and APC and RARb genes by employing a novel microfluidic rare-event screening protocol." (PMID 34581895, 2021). "The tumor gDNA target sequencing (DEPArray OncoSeek panel, Menarini Silicon Biosystems) confirmed the FGFR2 amplification and reported the same frameshift variant in APC, even though with a lower allele frequency (p.T1556Nfs∗3, AF: 14%), likely due to contamination by normal cells." (PMID 34178989, 2021). "We noted that while APC is only mutated in a substantial proportion of COAD samples, it is significantly hypermethylated in COAD along with several other cancer types (BLCA, BRCA, LIHC, LUAD, PRAD and UCEC), being hypermethylated in 50% of samples or more in several tumour types." (PMID 34871444, 2021).
tumor (continued). "In addition, the average levels of methylation across the 27,578 CpGs investigated were significantly lower in cell lines and primary tumors with APC mutations compared to cell lines and tumors without mutations in this important tumor suppressor gene." (PMID 33892786, 2021). "APC may be a tumor-suppressing gene involved in the earliest stage of CRC development." (PMID 31833958, 2020). "Further, through a process termed epistasis, an initial inactivation of APC might produce numerous intermixed subclones by sensitizing the tumor cell to the proliferative effects of acquired passenger-type mutations in cells that would otherwise not be affected by these mutations." (PMID 32079164, 2020). "Given that our statistical model only considered the SNV, tumor suppressors that can be inactivated by chromosomal deletions, such as APC, may not be adequately assessed for order of mutation." (PMID 29697365, 2018). "Notably, numerous TSGs were also reported to be hypermethylated in RCC samples compared to normal tissue (APAF-1, APC, BTG3, CDH1, Gamma-catenin, GATA-3, HOX-B-13, KILLIN, RARβ2, RASSF1A, TIMP3, VHL, and others), associating with increased tumor cell proliferation, invasion, and metastization." (PMID 29706891, 2018). "Notably, the cytotoxic effect of wild-type APC re-expression is rapid; suggesting that even partial inhibition of constitutively active trunk signalling could result in powerful anti-tumour effects." (PMID 29895949, 2018). "Functional domain analysis of APC-COMMD10 and RASA1-LOC644100 fusion genes showed truncation of APC (293 aa/325 aa) and RASA1 (179 aa/253 aa), respectively, which may induce loss of function of each tumour suppressor." (PMID 29955133, 2018). "As an alternative to APC, β-catenin, or RNF43 mutations, malignant intestinal epithelium may activate the Wnt pathway by gaining PTPRK-RSPO3 translocations which results in expression of tumor-cell derived RSPO33,13,19." (PMID 29127379, 2017). "In addition, these regions are thought to be required for β-catenin to interact with cell adhesion molecule E-cadherin, the tumour-suppressor gene adenomatous polyposis coli (APC) and α-catenin, as well as for the mediation of adherens junctions of the plasma membrane to the cytoskeleton." (PMID 28489928, 2017). "However, it is not clear which, if any, genetic alterations drive tumour initiation in the 10–15% of CRCs that do not carry APC or downstream WNT pathway mutations." (PMID 28695896, 2017). "Methylation-induced dysfunction of APC and subsequent activation of downstream pathways, such as the Wnt/β-catenin pathway, may be responsible for the aggressive tumor behavior.Consistent with the gene alteration types, the most common method of methylation detection is MSP or qMSP." (PMID 28009985, 2017). "Some of the interactions like APC and FEN1 may promote the cancer, adenomatous polyposis coli (APC) and Flap Endonuclease both are tumor oppressors but when APC interact with FEN1, this interaction inactivate the tumor suppressor activity and promote the cancer through novel mechanisms." (PMID 28187440, 2017). "The different distribution of APC-free and APC-bound Cdh1 in primary somatic cells versus tumor cells further indicates that Cdh1 might function differently via an APC-dependent or APC-independent mechanism in different cellular contexts, such as somatic versus tumor cells." (PMID 27462441, 2016).
tumor (continued). "Results show that the WNT targets were significantly activated in APC single-mutation tumours without allelic loss (Welch t-test P<0.0001), and in tumours with APC 2+ mutations (Welch t-test P=0.0004) or with single mutation plus allelic loss (Welch t-test P=0.011)." (PMID 27302369, 2016). "While there are other mechanisms that can account for this outcome, the findings described here highlight the possibility that a dissociation between the peptides generated by APC from those present on tumor may indeed be an obstacle to effective cancer recognition." (PMID 26885372, 2016). "To determine whether the WNT/β-catenin pathway might be activated in tumours with one APC-truncating mutation, we performed an immunohistochemical (IHC) analysis of 52 FFPE (formalin-fixed, paraffin-embedded) tumours (selected from 468 CRCs) with a β-catenin antibody." (PMID 27302369, 2016). "However, the variant frequency on APC gene in each tumor is not always the largest one in our study." (PMID 27121310, 2016). "The observation that vitamin D represses β-catenin signaling and that β-catenin activates the vitamin D receptor raise the possibility that impairment of the vitamin D pathway in vivo may affect the onset, incidence or progression of β-catenin-related neoplasias found in APC mutant mice." (PMID 27768599, 2016). "Thus while Axin can template βcat phosphorylation and can, at least in the presence of the truncated APC1 present in tumor cells, send it on to destruction, our data suggest APC promotes the rate at which βcat is transferred out of the destruction complex and sent to the proteasome." (PMID 26393419, 2015). "Therefore, it is not surprising that high-grade tumor budding is strongly associated with tumors arising from the tumors with mutation of the APC gene." (PMID 25806371, 2015). "Therefore, we used APC-mutant mice not only to quantitatively assess tumor frequency but also to understand molecular pathway alterations, which may have contributed to tumor development after radiation exposure." (PMID 26500891, 2015). "We earlier showed that not only did loss of wild-type APC increase resistance of HCT116 CRC cells to the effects of 5-FU, but that overexpression of mutant APC(1-1309) could increase 5-FU resistance in non-tumor HEK293 cells." (PMID 25301724, 2014). "APC regulates normal function of the Wnt/beta-catenin signaling pathway and also distinct from this pathway, functions as a mediator of apoptosis, cell cycle transition and the DNA damage/replication stress response and repair which influences its tumor suppressor activity." (PMID 25301724, 2014). "Interestingly, it has been reported that although APC or β-catenin mutations can be present in all the cells of a tumour, not all these cells display nuclear β-catenin." (PMID 23374535, 2013). "Our results demonstrating that stabilized endogenous β-catenin localizes to APC clusters at membrane extensions are generally consistent with studies in which an exogenous stabilized mutant β-catenin localized to MDCK protrusions but also extends these findings to tumor models." (PMID 23302090, 2013). "Intriguingly, APC+/min mice exhibiting whole-body SIRT1 deficiency developed a similar number of intestinal polyps as the APC+/min controls, but demonstrated significantly decreased average polyp size, indicating that SIRT1 could actually promote tumor growth." (PMID 23799088, 2013).
tumor (continued). "Indeed, APC exerts a variety of growth regulatory functions that, if disrupted, might lead to tumor formation." (PMID 23738079, 2013). "When a SIRT1 transgene was overexpressed in the intestinal epithelium, APC+/min mice developed fewer intestinal polyps, which was attributed to the increased deacetylation and nuclear exclusion of β-catenin and subsequently decreased proliferation rates of the tumor cells." (PMID 23799088, 2013). "Importantly, the migratory behavior of these tumor cells was also dependent on APC." (PMID 23302090, 2013). "The APC gene may act as a tumor suppressor following radiation damage." (PMID 26425572, 2013). "Interestingly, the tumor sample containing the LGR6 insGRS mutation also has mutation in APC but not in β-catenin, suggesting that the action of LGR6 does not depend on the genetic status of β-catenin." (PMID 22615920, 2012). "Seven additional tumours (6.8%) showed no mutation but had LOH at the APC locus." (PMID 21901162, 2011). "This may be particularly important during development of MSI and CIMP tumours due to the relative absence of APC mutation as a means to induce cytoplasmic β-catenin accumulation in these tumours." (PMID 21587258, 2011). "Six of 9 tumours with a BRAF mutation had no somatic APC mutation." (PMID 21901162, 2011). "Also, the vast majority of cases of normal breast and lung tissue display an un-methylated APC promoter 1A as compared to the corresponding tumours; consequently these are examples which illustrate the tumour-specific phenotype for APC promoter 1A methylation in some tissue types." (PMID 20208994, 2010). "Although the ability of APC to suppress canonical Wnt signaling by targeting β-catenin is critical for APC to suppress tumorigenesis, accumulating evidence suggests that APC likely suppresses tumor development through pathways besides inhibiting canonical Wnt signaling [see review]." (PMID 20368985, 2010). "Regulation of localised phospho-β-catenin may contribute to the tumour suppressor activity of APC." (PMID 21152425, 2010). "None of the blood samples, from both tumour types, contained APC mutations." (PMID 19293793, 2009). "However, the number of spontaneous somatic C:G > T:A transversions in the APC gene is significantly greater in tumor cells with biallelic MUTYH germline mutations compared to tumor cells without MUTYH mutations." (PMID 19506731, 2008). "However, it appears that analysis of APC/β-catenin expression in desmoid tumours might determine the efficacy of NSAIDs, and contribute to tumour-growth inhibition and survival in desmoid patients with β-catenin protein stabilisation." (PMID 18257933, 2008). "Conversely, in tumours lacking these APC mutations, activating missense mutations at one of the phosphorylation sites at codons 31, 33, 37 and 45 of exon 3 of the CTNNB1 gene (encoding the β-catenin protein) can render it stable as it can no longer be tagged for cellular degradation." (PMID 16356174, 2005). "Moreover, after exclusion of tumours displaying this overlap, a striking difference between occurrences of APC and/or K-ras mutations versus absence of hMLH1 expression was observed." (PMID 16356174, 2005). "Finally, although 11 tumours that harboured a mutation in the APC or K-ras gene also lacked hMLH1 expression, hMLH1 deficiency occurred more frequently in tumours that did not harbour these mutations (χ2 = 36.6, P < 0.001)." (PMID 16356174, 2005). "We generated a mouse model in which an HA tag was fused to the C terminus of APC, thereby disrupting the interaction with PTPN13, and this also resulted in increased tumor burden and reduced immune activity." (PMID 41486293, 2026). "This is because the APC11 peptide mimics the effect of APC overexpression, which can further enhance the inhibition of PTPN13 and the activation of IFNγ-STAT1 signaling in APC intact tumor cells, thereby enhancing the immune response." (PMID 41486293, 2026).